IL6 (interleukin 6)
Diseases named in the same sentence as IL6 in open-access papers (continued):
Sharing a sentence is not in itself a finding about the gene and the disease.
infection (continued). "CRP is a protein that is synthesized by hepatocytes and whose production is stimulated by cytokines, particularly interleukin-1 (IL-1), interleukin-6 (IL-6), and interleukin-17 (IL-17), in response to infection or tissue inflammation." (PMID 33158306, 2020). "Knockdown of TLT2 in monocytes followed by H37Rv infection impaired IL6 production apparently compared with other cytokines." (PMID 33042115, 2020). "The results indicated that infection of KP caused a significant increase in the secretions of TNF-α and IL-6 in mouse serum." (PMID 32625244, 2020). "The induction of IL-8, IL-6, CXCL2 and IL-1α upon infection was significantly suppressed by overexpressing the mutated PUF60." (PMID 32538777, 2020). "With increasing infection, the expression of IL-6 in LPS-DCs was lower than that in IRPS-DCs at 24, 48, and 72 h." (PMID 33028328, 2020). "Our results showed that the levels of inflammatory cytokines, such as IFN-γ, IL-6, and IL-12, in the sera of infected mice peaked at about 6 weeks post-infection, which showed that the mice were undergoing an inflammatory response." (PMID 33330140, 2020). "We used qPCR to measure the gene expression of the NF-κB–activated genes IL-8 and IL-6 as well as the interferon-stimulated genes (ISGs) IFIT1 and IFIT2 in MyD88-deficient cells and MyD88-intact cells during DENV2 infection." (PMID 32117091, 2020). "Infection of human whole blood with any Candida species led to the release of IL-8 and proinflammatory cytokines (IL-1β, IL-6, TNF-α)." (PMID 33024045, 2020). "Despite the reduced dose of virus, old mice still had worse lung injury as measured by bronchoalveolar lavage protein content 10 days after infection and increased levels of IL‐6 in bronchoalveolar lavage fluid and in the plasma compared with young mice." (PMID 32720752, 2020). "The secretion of cytokines, mainly IL-6 and IL-1β, also promotes the recruitment of other immune cells, mainly monocytes and T lymphocytes, to the infection sites." (PMID 32781571, 2020). "Consistent with the higher levels of plasma IL‐6, the increase in skeletal muscle atrogin‐1 occurred more rapidly in old animals, but was similar 10 days after infection in young and old mice." (PMID 32720752, 2020). "For the diagnosis of PJI, Di Cesare and colleagues found that serum IL-6 had a higher diagnostic accuracy compared with CRP and ESR in diagnosing infection following hip and knee replacement (97% and 83%, 69%, respectively)." (PMID 33008442, 2020). "In the murine model of infection, an inhibition of IL-6 production in L. amazonensis–infected macrophages was observed." (PMID 32596164, 2020). "Network pharmacology showed that IL-6 was a remarkable predicted target which was related with infection." (PMID 32493296, 2020). "Only in the context of murine type 2 diabetes was IL-6 described to be produced after infection by natural killer cells and CD11c DC." (PMID 33334075, 2020). "Additional surrogate parameters indicating systemic inflammation and infection such as interleukin 6, interleukin 8, and procalcitonin are regularly determined in none, 4% (2/51), and 22% (11/51) of all centers." (PMID 32524514, 2020). "And then cytokines such as IL-6, IL-8 and IL-17 are produced to help epithelial growth and angiogenesis locally, which have been identified in the development of CRC as a result of infection with pathogenic bacteria in mice." (PMID 32228650, 2020). "At 5 d after infection, most cytokines had tapered back to baseline levels and only IL-6 and G-CSF remained upregulated in males." (PMID 32373108, 2020). "A positive band was only detected in the AdV 7 infected cells pulled down by anti-p65 antibody, but not in either mock-infected samples or control IgG pulled down samples, indicating that upon AdV 7 infection, NF-κB can bind onto IL-6 promoter." (PMID 33072092, 2020).
infection (continued). "IL6 transcription level was also assessed in CSFV Shimen-infected PAMs to identify the inflammatory responses triggered in response to infection, and a similar trend of increased transcriptional level was observed." (PMID 32110485, 2020). "IL-6 is a cytokine that is not only involved in inflammation and infection responses but also in the regulation of metabolic, regenerative and neural processes." (PMID 32704142, 2020). "On day 10 after infection, all four groups of animals displayed similar bacterial loads in kidney tissues as well as similar serum levels of interleukin-6 (IL-6) and monocyte chemoattractant protein 1 (MCP-1)." (PMID 33203754, 2020). "At the time of infection, IL-6 and ITQ were generally the most sensitive markers; however, in subsequential labs, CrP was the most sensitive marker." (PMID 32447562, 2020). "We found increased IL-6 expression in koalas with exogenous infections (both KoRV-B and KoRV-C), findings indicative of inflammation." (PMID 33316950, 2020). "A significant increase in IL-6 gene expression was observed in CFBE41o- cells at 2 hours in response to infection with P. histicola (p<0.001)." (PMID 33031374, 2020). "IL-6 is the dominant mediator of the acute phase response, an innate immune mechanism that is triggered by infection and inflammation." (PMID 33171870, 2020). "In Tulahuen strain infection, IL-6/pSTAT3 protects cardiomyocytes through upregulation of anti-apoptotic factor Bcl-2, thus maintaining the survival of the host cell that is beneficial for parasite persistence." (PMID 32626662, 2020). "A similar increase in IL-6 expression was observed in the adjuvant-only vaccinated, challenged group, but partially mediated by Bp-WCV, suggesting that IL-6 production is mainly triggered by infection with B. pertussis, consistent with previous findings." (PMID 33153066, 2020). "In our previous study, Toxoplasma gondii VLP-immunized mice demonstrated significantly lessened IFN-γ and IL-6 production following T. gondii challenge infection compared to the unimmunized control group." (PMID 32751598, 2020). "As a pro-inflammatory cytokine, IL-6 is involved in the recruitment of immune cells, including lymphocytes and circulating monocytes, to the site of infection." (PMID 32156313, 2020). "At 5 days after infection, IL-6 and G-CSF were increased in males, whereas IL-5 and G-CSF were reduced in S. epidermidis infected females compared to control animals." (PMID 32373108, 2020). "IGF1 decreases in response to pro-inflammatory cytokines, such as tumor necrosis factor-α, interleukin (IL) 1β, and IL-6; low circulating levels of IGF1 are associated with infection, trauma, and aging." (PMID 32692761, 2020). "We next examined the effect of exogenous IL-6 treatment at varying concentrations on intracellular P. gingivalis levels in GECs at 6 h post-infection where we observed the highest IL-6 production during the infection." (PMID 32419582, 2020). "In a previous report, specific pathogen free (SPF) chickens inoculated with a high-virulence C. psittaci strain were determined to have high IL-10 and IL-6 expressions, which resulted in immune suppression and secondary infection of H9N2." (PMID 32183481, 2020). "These factors are critical for virulence and, during infection, induce secretion of interleukin-6, CXCl1, and CXCL2, assist with bacterial dissemination to the spleen, and stabilize hypoxia inducible factor-1a (HIF-1a)." (PMID 32390954, 2020). "It has been recently reported that IL-6 plays an important role in rendering protective immune response against SbRLD mediated infection by lowering IL-10 level." (PMID 33240825, 2020). "Interleukin-6 (IL-6) is a pleiotropic cytokine promptly produced in response to infections, which contributes to host defense through the stimulation of acute phase immune responses." (PMID 33322581, 2020).
infection (continued). "Upon infection, both cytokines (TNFα and IL6) and chemokines (KC and MCP1) levels were significantly increased in Ccn1flox/flox mice, whereas this inflammatory response was greatly reduced in Ccn1ΔMyeloid mice." (PMID 32144270, 2020). "IL6 is an inflammatory protein that plays an important role in host immunity, particularly during the acute phase of the infection." (PMID 32964195, 2020). "Previous reports suggest that adenosine produced by ectonucleotidase, during activation of the ATP pathway, during infection contributes to the production of IL-10 and IL-6." (PMID 32555598, 2020). "At 16 h post-infection, a mean of 16.05% ± 2.51% (standard deviation) and 15% ± 1.21% of BMMCs were positive for IL-6 and TNF-α, respectively." (PMID 33261178, 2020). "Data emerging from China have demonstrated that in almost all cases of severe infection, high levels of IL-6 and many other pro-inflammatory cytokines (predominantly downstream of NF-kB) and TNFα were detected." (PMID 32797326, 2020). "The previous cytokine profile study following MHV68 infection shows that spleen from infected mice produces a high-level of IL6 and IFN-γ, whereas in vitro infection of naïve splenocytes induces IL16 and IL10." (PMID 32735617, 2020). "In villous explants, the AgNp-Bio treatment downregulated production of IL-4, IL-6, and IL-8 after infection." (PMID 33552033, 2020). "IL-6, promptly and transiently produced in response to infections and tissue injuries, contributes to host defence through the stimulation of acute phase responses, hematopoiesis, and immune reactions." (PMID 32256705, 2020). "Overall, these findings support that CD73 can be a key determinant for IL-6 secretion stimulated by the danger signal eATP-mediated ROS production in GECs upon infection." (PMID 32419582, 2020). "In this study, we provided new insights on the relationship between IL-6 and B. abortus in vivo infection." (PMID 33322581, 2020). "In the intestine BALB/c mice the infection with Y increased Ifng / Il6 expression, but with VFRA there was an increased in Cd4 / Tnf which was protective." (PMID 32925918, 2020). "Both nasal and bronchial HAE models of superinfection were further characterized and validated in terms of viral production, impact on trans-epithelial resistance, and apical release of IL-6, which we used as hallmarks of infection." (PMID 33322535, 2020). "On day 5 post infection the Th2 cytokine IL-5 and the pro-inflammatory cytokine IL-6 were massively upregulated in IFN-γOFF mice as well as G-CSF and CCL-5 when compared with infected WT controls." (PMID 32023327, 2020). "Following infection with Escherichia coli, cytokine expression of IL-1β, IL-6, TNF-α, and IL-10 in the intestinal mucosa significantly increases, resulting in piglets having greater villous atrophy and intestinal morphology disruption." (PMID 32547405, 2020). "In contrast, 36 days after infection, more than 3 weeks after parasite clearance, IL-6 and TNF-α production was significantly increased upon stimulation with LPS, C. albicans and S. aureus compared to baseline." (PMID 33324683, 2020). "A possible explanation for these outliers, next to chance, is temporarily high IL-6 levels in the context of infection." (PMID 33362560, 2020). "After infection, in essence, IL-6 is produced by many cell types of which the most important are monocytes and macrophages and is believed to play a central role in hosts defense mechanisms against various infectious agents." (PMID 33334075, 2020). "The increased secretion of the proinflammatory cytokines IL-6 and IL-1α as host defense after infection with S. aureus was also observed in 2D and 3D cell models." (PMID 33302597, 2020). "IL-6, secreted by macrophages, is a known pyrogen and a potent stimulator of the acute phase reactants following infection or trauma." (PMID 32251301, 2020).
infection (continued). "At 24 h post-infection, brains (hippocampus and cerebral cortex) were harvested to examine the expression of proinflammatory factors (Tnf-α, Il-1β, and Il-6) by RT-PCR." (PMID 32676082, 2020). "IL-6 related biomarkers are elevated in both inflammation and infection and are correlated to CSF white cell numbers." (PMID 33409494, 2020). "IL-6 is one of the pro-inflammatory cytokines, and is detected in serum in the early stages of infections." (PMID 33233806, 2020). "Our results show that co-treatment with DATs limited the production of G-CSF and IL-6 by WT Mtb infected epithelial cells, similar to the responses observed when Δmmpl7 mutant single infection and coinfections were carried out." (PMID 32695111, 2020). "enterica and found that 6 days after infection, the expression of IL-6 mRNA in the cecal tonsils was upregulated when compared with that in the Cont and ProSal group chickens." (PMID 32054193, 2020). "Reduced levels of TNF and IL-6 by anti-EDII-cEDIII Ab treatment were observed in the liver during infection of various serotypes of DENV, excluding DENV3." (PMID 32075300, 2020). "Dysregulated and continual synthesis of IL-6 has been shown to play a pathological role in chronic inflammation and infection." (PMID 32425950, 2020). "The relative number of these antigen-specific TH17 cells was almost constant over the entire course of infection in both groups but was significantly reduced in IL-6−/− mice 98 days after Mtb infection." (PMID 33375150, 2020). "infection of HEKs increased the mRNA expression of the IL6 gene very significantly (18.78‐fold; P ≤ .001), compared with C. t." (PMID 31912662, 2020). "Given the putative role of CD73 for promoting intracellular P. gingivalis growth and inhibiting eATP-mediated antimicrobial IL-6 secretion during infection in GECs, we studied the potential direct effect of IL-6 on intracellular P. gingivalis survival." (PMID 32419582, 2020). "The infection resulted in an increase of TNF-α or IL-6 mRNA expression in the hippocampus and cortex of infected WT mice." (PMID 33121515, 2020). "IL-6 KO infected macrophages showed similar levels of IL-12 secretion in all infection conditions analyzed, compared to wild-type infected macrophages." (PMID 33322581, 2020). "When infection or tissue damage occurs, IL-6 is rapidly produced by monocytes and macrophages; and it helps remove infectious agents and restore damaged tissues by activating immunity, blood, and acute phase reactions." (PMID 32677975, 2020). "Interleukin 6 (IL-6) is secreted by T cells and macrophages to stimulate immune response after infection and trauma." (PMID 32104715, 2020). "Macrophages secrete IL-6 during infection, and IL-6 can induce cholangiocyte proliferation leading to ductular reaction." (PMID 32362892, 2020). "For instance, deficiency of IL-6 in C57BL/6 mice has been reported to cause colonic damage, increase infiltrate of inflammatory cells and apoptosis during infection with C. rodentium." (PMID 33392105, 2020). "Infection by the related SARS-CoV induces a dose-dependent production of IL-6 from bronchial epithelial cells." (PMID 32668803, 2020). "Taken together, our data in the current study have shown that AdV 7 infection triggers the production of a range of inflammatory cytokines in the airway in children, with IL-6 showing the highest elevation." (PMID 33072092, 2020). "It has been reported that in the activation of the defense mechanisms, the production of TNF-α, along with IL-1β and IL-6, induces a protective inflammatory response for infection control." (PMID 32423093, 2020). "In the current study, WBC, CPR, PCT and IL-6 were chosen as indicators of the infection and inflammatory response." (PMID 32640995, 2020). "In this context, one of the key cytokines involved in infection-induced cytokine storm is interleukin 6 (IL-6)." (PMID 32903349, 2020).
infection (continued). "Various infection factors stimulate macrophages and neutrophils to produce IL-6, TNF-α, and other pro-inflammatory transmitters." (PMID 32625095, 2020). "After bacterial infection, the level of IL-6 increased rapidly and reached the peak at 2 h, which was consistent with the severity of infection." (PMID 32493296, 2020). "In contrast, IL-1β (P = 0.0324, P = 0.0126) and IL-6 (P = 0.0340, P = 0.0077) in lung was significantly lower at 5 days after infection." (PMID 33603716, 2020). "Infection with inflammatory environment can prolong QT interval due to the effect of inflammatory cytokines (interleukin-6, tumor necrosis factor-α, interleukin-1) on potassium and calcium channels." (PMID 32154029, 2020). "We observed limited and transient changes in cytokine transcription after infection, i.e., upregulation of IL-6 at 3 hpi, and of GM-CSF at 3 and 6 hpi, and downregulation of M-CSF at the latest time point (9 hpi)." (PMID 33121170, 2020). "Further, our study findings indicate that CPLE treatment modulates the infection induced cytokine levels of TNFα, IFNγ, IL6 and IL4." (PMID 32074143, 2020). "IL-6 mRNA expression was markedly upregulated by S. agalactiae in a time-dependent manner after 1 h post-infection (p < 0.01)." (PMID 32746898, 2020). "The median value changes in the IL-6 was 7.91 pg/L (IQR 4.26–13.76 pg/L) for those patients who remained infection-free and 8.81 pg/L (IQR 3.55–15.56 pg/L) for those who experienced reinfection (p = 0.948)." (PMID 32887615, 2020). "IL-1α, IL-1β, IL-4, and IL-6 showed infection-specific relative responses, with higher levels in septic TKR than both aseptic TKR and primary TKA (p < 0.05)." (PMID 32708756, 2020). "Upon infection with β-coronavirus monocytes, macrophages, and dendritic cells get activated and start the secretion of prominent pro-inflammatory cytokine, like IL-6 along with other inflammatory cytokines." (PMID 32850977, 2020). "The levels of IFN-γ, IL-12, and IL-6 in mouse serum peaked at 6 weeks post-infection, and IL-10 and IL-21 levels peaked at 8 weeks post-infection." (PMID 33330140, 2020). "The inflammatory cytokines IL-1β and IL-6 as well as TNFα showed similar trends of increase in both infection protocols, albeit with more prominent increases of TNFα under SARS-CoV-2 infection." (PMID 33163005, 2020). "In accordance with these data, confocal images showed similar levels of intracellular B. abortus–GFP in wild-type and IL-6 KO macrophages 24 h post-infection." (PMID 33322581, 2020). "The pro-inflammatory cytokine IL-6 plays vital roles in the inflammatory process during infection, and is involved in the pathogenesis of several immune-related diseases." (PMID 32393780, 2020). "As expected, elevated concentrations of proinflammatory cytokines were observed during the acute phase of infection in the severe group, including IL-1α, IL-6, IL-8, IL-16, and TNF-α." (PMID 32990499, 2020). "The level of IL-6 mRNA in the lungs of klotho WT mice slightly increased at 1 day post-infection and subsequently deceased at 3 days post-infection." (PMID 33329595, 2020). "Daily treatment with artesunate, started two weeks after the infection, was able to significantly reduce IL-1β, IL-6, and TNF-α levels in paw tissue." (PMID 32230725, 2020). "Excessive IL-6 and corticostrone expression was increased by stressors such as immobilization and pathogen infection via the activation of the HPA axis." (PMID 32158447, 2020). "IL-6 s in BALFs from MP single infection group were significantly higher than those from control (p < 0.05)." (PMID 32393186, 2020). "For example, the increased parasite load in IL-6 and NOD2-deficient mice, which show a delayed neutrophil recruitment at the site of infection, is overcome by subcutaneous infection, resulting in a worm burden comparable to that of immunocompetent WT mice." (PMID 33160409, 2020).